NRL (neural retina leucine zipper)
Description:
Acts as a transcriptional activator which regulates the expression of several rod-specific genes, including RHO and PDE6B. Also functions as a transcriptional coactivator, stimulating transcription mediated by the transcription factor CRX and NR2E3. Binds to the rhodopsin promoter in a sequence-specific manner.
Synonyms: D14S46E; RP27; NRL-MAF; ESCS2
Tractability: PROTAC: UniProt records ubiquitination sites on it.
Gene: Protein-coding gene on chromosome 14 (24,078,662 to 24,115,010, reverse strand). Ensembl gene ENSG00000129535.
Subcellular location: Cytoplasm; Nucleus
Subcellular location (Human Protein Atlas): Nucleoplasm; Cytosol
Gene Ontology:
Molecular function: DNA-binding transcription activator activity, RNA polymerase II-specific; leucine zipper domain binding; protein binding; RNA polymerase II cis-regulatory region sequence-specific DNA binding; sequence-specific double-stranded DNA binding; DNA binding; DNA-binding transcription factor activity, RNA polymerase II-specific; DNA-binding transcription factor activity; promoter-specific chromatin binding
Biological process: positive regulation of transcription by RNA polymerase II; regulation of transcription by RNA polymerase II; retinal rod cell development; visual perception; regulation of DNA-templated transcription
Cellular component: cytoplasm; nucleoplasm; nucleus; chromatin
Genetic constraint (gnomAD): Loss-of-function variants: 24 observed, 15.82 expected, observed/expected ratio (o/e) 1.52, 90% interval 1.09 to 1.92. The upper end of that interval is the gene's LOEUF score, 1.92, which puts it in group 6 of 6, group 1 being the genes least tolerant of losing a copy. Missense variants: 314 observed, 287.32 expected, observed/expected ratio (o/e) 1.09, 90% interval 1 to 1.2. Synonymous variants: 142 observed, 126.71 expected, observed/expected ratio (o/e) 1.12, 90% interval 0.98 to 1.29.
Gene-disease validity (ClinGen):
ClinGen rates the evidence that NRL causes each of these diseases.
retinitis pigmentosa 27 (autosomal dominant): Definitive.
Homologues: Orthologues: chimpanzee NRL (100% identical), macaque NRL (98% identical), guinea pig NRL (93% identical), rabbit NRL (93% identical), pig NRL (93% identical), rat Nrl (90% identical), mouse Nrl (89% identical), dog NRL (76% identical), zebrafish nrl (52% identical), Drosophila melanogaster tj (39% identical), Drosophila melanogaster maf-S (20% identical), Caenorhabditis elegans maf-1 (19% identical). Paralogues in human: MAF (56% identical), MAFA (54% identical), MAFB (54% identical), MAFK (24% identical), MAFF (23% identical), MAFG (22% identical).
Diseases named in the same sentence as NRL in open-access papers:
NRL is named in the same sentence as 37 diseases in open-access papers, as found by Europe PMC text mining. Sharing a sentence is not in itself a finding about the gene and the disease. The quoted sentences say what the papers report.
retinitis pigmentosa (13 papers, 2017 to 2024). Retinitis pigmentosa (RP) is an inherited retinal dystrophy leading to progressive loss of the photoreceptors and retinal pigment epithelium and resulting in blindness usually after several decades. "NRL mutations have been associated with retinitis pigmentosa and mutations in Blimp-1, RORβ, Otx2, Crx, or Nrl are associated with a loss of rod PRs in mammals." (PMID 36960411, 2023). "Autosomal dominant missense variations in the NRL gene have been reported to cause retinitis pigmentosa (RP), while autosomal recessive variations of the NRL gene have been described, so far, in only eight patients belonging to six unrelated families." (PMID 36140584, 2022). "NRL (Neural Retina Leucine Zipper) mutations also cause enhanced S-cone syndrome and retinitis pigmentosa, as it is critical for rod fate determination and maintenance." (PMID 34638582, 2021). "Neural retina leucine zipper (NRL) is critical for rod photoreceptor genesis and degeneration, with NRL mutations known to cause enhanced S-cone syndrome and retinitis pigmentosa." (PMID 32081919, 2020). "NRL is a factor important for rod photoreceptor cell differentiation and homeostasis, which is regarded as a therapeutic target to treat retinitis pigmentosa." (PMID 39125773, 2024). "Fourth, gene therapy strategies that disrupt NRL show substantial promise in mouse models as a cure for retinitis pigmentosa and other rod degenerative disease – a mechanism to save degenerating rods by converting them into a cone-like state." (PMID 33299975, 2020). "In conclusion, inhibition of the NRL/NR2E3 pathway represents an intriguing approach for the treatment of retinitis pigmentosa." (PMID 32668775, 2020). "For example, many genes with causative mutations leading to Retinitis Pigmentosa, including RHO, NRL, and NR2E3 demonstrated foveal rod enrichment." (PMID 32555229, 2020). "In addition, mutations in genes known to cause primary rod dysfunction and death (e.g., retinitis pigmentosa) could be edited into the NRL+/eGFP line, allowing rapid and accurate assessment of rod-specific outcomes relative to the unedited, isogenic NRL+/eGFP line." (PMID 29402929, 2018). "Our data suggest that CRISPR/Cas9-mediated NRL disruption in rods may be a promising treatment option for patients with retinitis pigmentosa." (PMID 28291770, 2017). "Wdr17 is a candidate for the RP29 form of Retinitis Pigmentosa and has binding sites for CRX and NRL close to the rod TSS." (PMID 28640837, 2017).
retinal degeneration (8 papers, 2007 to 2025). Degeneration of the retina. "CRISPR-Cas9 engineered NRL-deficient ESC retinal organoids exhibit an abnormal number of photoreceptors expressing S-Opsin.AAV-delivered CRISPR-cas9 Nrl gene knockdown in RHO-P347S Rd10 mice prevents retinal degeneration." (PMID 36840007, 2023). "When the adult NRL knockout experiment was repeated on the Rho-/- retinal degeneration mouse model at P25, the knockout prevented retinal degeneration, preserved retinal laminar architecture, and restored photopic cone ERG physiology when assayed at P90." (PMID 32668775, 2020). "Additional questions include: what is the optimal timing of NRL deletion during retinal degeneration?" (PMID 32668775, 2020). "Taken together, NRL/NR2E3 pathway mutations alter the balance of normal photoreceptor differentiation in the developing retina, leading to a loss of rod function and retinal degeneration." (PMID 32668775, 2020). "Since mutations in NRL and CRX are involved in inherited retinal degenerations, SP4 was considered a good candidate for mutation screening in patients with this type of diseases." (PMID 17356515, 2007). "A pragmatic therapeutic goal for RP patients would be the reprogramming of rod photoreceptors to avoid manifestations of retinal degeneration, rather than phenocopying germline NRL or NR2E3 mutations." (PMID 32668775, 2020). "Importantly, there did not appear to be any change in the wiring of the rods, increased ERG response to short wavelengths, or retinal degeneration, which occurs in germline NRL-/- mice." (PMID 32668775, 2020). "One other unanswered question is whether long term inhibition of the NRL pathway will lead to deleterious effects on the retina such as retinal degeneration." (PMID 32668775, 2020). "Thus, in multiple mouse models, adult knockout of NRL appears to slow the rate of retinal degeneration and preserve crucial aspects of visual-cycle physiology, suggesting a potential target for further exploration in human RP." (PMID 32668775, 2020). "Importantly, deleterious phenotypes such as retinal degeneration seen in human patients with germline mutations of NRL or NR2E3 have not been observed in long-term deletion of NRL in mature retina in mouse models." (PMID 32668775, 2020). "In both NRL and NR2E3 mutant mouse models, failure to fully specify rod-photoreceptors leads to retinal degeneration." (PMID 40758714, 2025). "Under the control of the NRL promoter, NR2E3 expression in rd7 NR2E3-/- mice prevented retinal degeneration, supporting the hypothesis of NR2E3 favoring rod homeostasis." (PMID 32668775, 2020). "Importantly, deletion of NRL in adult photoreceptors did not appear to cause deleterious effects such as photoreceptor degeneration even after six months, suggesting that this therapy may not cause retinal degeneration." (PMID 32668775, 2020). "Importantly, adult CRISPR/Cas9 NRL knockout mice lacked the deleterious phenotypes of retinal lamination, retinal degeneration, and vascular and RPE changes characteristic of NRL germline knockout." (PMID 32668775, 2020).
retinal dystrophies (6 papers, 2012 to 2024). "The NRL gene is located on chromosome 14 and has been linked to inherited retinal dystrophies (IRDs)." (PMID 39766861, 2024). "Most missense variations in the NRL gene are dominant and have been reported to cause RP, while retinal dystrophies caused by autosomal recessive NRL variants are scarce." (PMID 36140584, 2022). "Of these, 22 NRL targets are associated with human retinal dystrophies, whereas 95 mapped to regions of as yet uncloned retinal disease loci." (PMID 22511886, 2012). "The retinal changes with a clumped pattern at the level of the RPE, mainly along the temporal vascular arcades, are typical for NRL- or NR2E3-related retinal dystrophy." (PMID 39766861, 2024). "The subnetwork retrieved after querying for three retinal-specific transcription factors (shortest path between NRL and NR2E3, plus addition of CRX) allows showing their connection to other causative retinal dystrophy genes." (PMID 31712826, 2019).
retinoblastoma (6 papers, 2016 to 2025). A malignant tumor that originates in the nuclear layer of the retina. "This idea is further supported by the retinoblastoma cells’ preferential expression of cone-enriched truncated NRL transcript isoforms." (PMID 40767624, 2025). "However, retinoblastoma cells also express rod lineage factor NRL RNAs, which – along with other evidence – suggested a heretofore unexplained connection between rod gene expression and retinoblastoma development." (PMID 40767624, 2025). "To assess endogenous Tr-NRL expression, we performed immunoblot analysis of CHLA-VC-RB31 retinoblastoma cells, which were predicted to express FL-NRL and Tr-NRL transcripts in a cone-like 0.73:1 ratio, with an antibody that recognizes both FL-NRL and Tr-NRL proteins." (PMID 40767624, 2025). "However, the early L/M cone precursors’ expression of NR2E3 and NRL RNAs suggests that their presence in retinoblastomas reflects their normal expression in the L/M cone precursor cells of origin." (PMID 40767624, 2025). "Several rod photoreceptor-specific genes whose expression is known to be depleted in retinoblastoma were downregulated, but not NRL and GNB1." (PMID 33270844, 2020). "We transfected the rho-Gluc reporter with either shEGFP, shPIAS2_49 or shPIAS2_50, with and without the CRX and NRL expression vectors, into monkey kidney (COS7) and two human retinoblastoma cell lines (WERI-Rb, Y79)." (PMID 27977714, 2016).
autosomal dominant retinitis pigmentosa (5 papers, 2011 to 2024). Autosomal dominant retinitis pigmentosa (RP) is an autosomally dominant inherited retinal dystrophy leading to progressive loss of the photoreceptors and retinal pigment epithelium and resulting in blindness usually after several decades. "Pathogenic variants in the gene encoding NRL have been associated with autosomal dominant retinitis pigmentosa and autosomal recessive clumped pigmentary retinal degeneration." (PMID 39766861, 2024). "Mutations in NRL are associated with the autosomal recessive enhanced S-cone syndrome and autosomal dominant retinitis pigmentosa." (PMID 35245286, 2022). "Variants in NRL have been described in autosomal dominant retinitis pigmentosa patients and may, therefore, have the potential to explain the patient’s phenotype, as the frequency is quite rare in gnomAD (1/250,000 alleles)." (PMID 37107692, 2023). "In humans, missense mutations in NRL are associated with autosomal dominant retinitis pigmentosa." (PMID 21897746, 2011). "Gain-of-function variants at amino acid positions 49, 50, 51, and 96 have been shown to reduce NRL phosphorylation and/or increase rhodopsin promoter activation, leading to autosomal dominant retinitis pigmentosa (adRP, OMIM #613750)." (PMID 39766861, 2024). "There are at least five genes, RHO, NRL, NR2E3, CRX, and RP1, associated with both autosomal dominant retinitis pigmentosa (ADRP) and autosomal recessive retinitis pigmentosa (ARRP)." (PMID 25692141, 2015).
enhanced S-cone syndrome (4 papers, 2009 to 2024). An autosomal recessive retinopathy in which patients have increased sensitivity to blue light; perception of blue light is mediated by what is normally the least populous cone photoreceptor subtype, the S (short wavelength, blue) cones. "Enhanced S-cone syndrome (ESCS) is a rare type of retinal dystrophy disorder that is linked to NR2E3 gene mutation and NRL gene mutations less widely." (PMID 37719593, 2023). "Mutations in the NRL and NR2E3 genes encoding rod-specific transcription factors exemplify this diversity, as autosomal dominant, autosomal recessive, and sporadic mutations have been implicated in RP and the related IRD, enhanced S-cone syndrome (ESCS)." (PMID 32668775, 2020). "Conversely, loss-of-function variants in NRL have been found in patients affected by autosomal recessive clumped pigmentary retinal degeneration, which resembles the clinical phenotype caused by autosomal recessive variants in NR2E3, also known as enhanced S-cone syndrome (ESCS, OMIM #268100)." (PMID 39766861, 2024). "The corresponding human disease, enhanced S-cone syndrome (ESCS), may either be caused by a lack of NRL or NR2E3, a transcription factor with overlapping functions to NRL." (PMID 19838301, 2009).
night blindness (3 papers, 2018 to 2025). Inability to see clearly in dim light. "Other authors have described patients with Ser50Thr mutations in NRL and adRP as exhibiting night blindness symptoms from birth to 16 years and subjective loss of peripheral vision between ages 20–37 years." (PMID 39766861, 2024). "In humans, disruption of either NRL or NR2E3 expression causes enhanced S-cone syndrome, characterized by supranormal blue cone function due to an increased proportion of S-cones and night blindness due to the absence of rod-photoreceptors." (PMID 40758714, 2025).
retinal diseases (3 papers, 2007 to 2012). "We identified 21 NRL target genes that are known to be associated with retinal diseases involving photoreceptor degeneration." (PMID 22511886, 2012). "Interestingly, knockdown of 16 target genes, reported in this study, resulted in photoreceptor cell death or abnormal morphology, highlighting the importance of NRL targets in maintaining normal physiology and the association of perturbed target gene expression with retinal diseases." (PMID 22511886, 2012). "Our studies establish NRL and CRX as the key regulatory nodes for rod-expressed genes, identify NRL targets as candidate genes for retinal diseases, and provide a framework for GRN that controls homeostasis in rod photoreceptors." (PMID 22511886, 2012). "Furthermore, almost 100 human NRL target genes map within the critical region of 29 as yet uncloned retinal disease loci." (PMID 22511886, 2012).
blinding (2 papers, 2015 to 2020). "Second, mutations in the NRL gene (along with its downstream effector NR2E3) are causal of blinding disorders that remain unchecked." (PMID 33299975, 2020).
breast cancer (2 papers, 2011 to 2023). A primary or metastatic malignant neoplasm involving the breast. "Despite the clear relevance of genetic aberrations in human breast cancer progression and the wide use of mouse models to study human breast cancer in vivo, relatively few mouse models of breast cancer have been characterized at the genome level, barring MMTV-PyMT, MMTV-Neu, and NRL-PRL models." (PMID 37805590, 2023).
hyperopia (2 papers, 2018 to 2022). A refractive error in which rays of light entering the eye parallel to the optic axis are brought to a focus behind the retina, as a result of the eyeball being too short from front to back. "Additionally, another frequently reported homologous clinical sign is the presence of elevated hyperopia in NR2E3-associated ESCS and NRL-associated ESCS." (PMID 36140584, 2022).
medulloblastoma (2 papers, 2009 to 2014). A malignant, invasive embryonal neoplasm arising from the cerebellum. "The early rod precursor-specific transcripts, CRX and NRL were exclusively and strongly over-expressed by Group 3 medulloblastoma." (PMID 25412507, 2014).
oculopharyngeal muscular dystrophy (2 papers, 2020 to 2022). Oculopharyngeal muscular dystrophy (OPMD) is an adult-onset progressive myopathy characterized by progressive eyelid ptosis, dysphagia, dysarthria and proximal limb weakness. "There are few reports of autosomal recessive RP due to NRL, with one report describing patients with homozygous mutations in both NRL as well as PABPN1, a cause of oculopharyngeal muscular dystrophy." (PMID 32668775, 2020).
depression (1 paper, 2020). "NRL is associated with depression in lung cancer both in terms of severity and clinical significance." (PMID 34056574, 2020). "We hypothesize that NLR will be elevated in depressed patients with lung cancer and that both elevated NRL and depression will have prognostic implications." (PMID 34056574, 2020).
epilepsy (1 paper, 2018). A brain disorder characterized by episodes of abnormally increased neuronal discharge resulting in transient episodes of sensory or motor neurological dysfunction, or psychic dysfunction.
HELLP syndrome (1 paper, 2019). A life-threatening condition that can potentially complicate pregnancy. "The modifications in NLR and PLR have been extensively studied in hypertensive disorders of pregnancy, but ours is the first study comparing NRL and PLR between patients with HELLP syndrome (excluding mere preeclampsia) and women with healthy third-trimester pregnancies." (PMID 31072037, 2019).
hyperglycaemia (1 paper, 2025). "Notably, transcription factors critical for photoreceptor development, such as CRX and NRL, remained unchanged, suggesting that hyperglycaemia selectively impairs photoreceptor terminal differentiation and function rather than their initial specification." (PMID 41419458, 2025).
Nystagmus (1 paper, 2022). Rhythmic, involuntary oscillations of one or both eyes related to abnormality in fixation, conjugate gaze, or vestibular mechanisms. "No patients with nystagmus were reported, whereas one of our patients was affected, suggesting a younger age of onset or a more severe presentation in some cases of NRL-associated ESCS as compared with NR2E3-related ESCS." (PMID 36140584, 2022).
type 2 diabetes (1 paper, 2020). "The cT1-increasing allele in rs111723834 (missense variant in PCK2, also an intronic variant in NRL) was associated with lower aminotransferases, lower risk of type 2 diabetes, and lower triglycerides." (PMID 32247823, 2020).